ALKBH5 (alkB homolog 5, RNA demethylase)
Diseases named in the same sentence as ALKBH5 in open-access papers (continued):
Sharing a sentence is not in itself a finding about the gene and the disease.
lung adenocarcinoma (continued). "Similarly, hypoxia and HIFs elevate ALKBH5 expression in lung adenocarcinoma cells, renal cell carcinoma cells, endometrial cancer stem cells and pituitary adenoma cells, leading to invasive tumor phenotype, enhanced tumor initiation capacity, sustained stem-like state and poor clinical outcomes." (PMID 35063010, 2022). "To test this, we analyzed the expression of the demethylation enzymes ALKBH5 and FTO in lung adenocarcinoma and normal tissues using the TCGA database." (PMID 39990663, 2025). "The ALKBH5-m6A–FOXM1 signaling axis has also been reported to promote proliferation and invasion of lung adenocarcinoma cells." (PMID 35279083, 2022). "Among these genes, KIAA1429, HNRNPC, YTHDC2, METTL3, WTAP, YTHDC1, and FTO were down expressed in lung adenocarcinoma, RBM15, ZC3H13, YTHDF1, YTHDF2, and ALKBH5 were up expressed." (PMID 32398949, 2020). "Next, we analyzed the expression levels of ALKBH5 in different tumor tissues and normal tissues using the TNM plot website and found that ALKBH5 was highly expressed in most tumor tissues, including lung adenocarcinoma (LUAD) and lung squamous cell carcinoma (LUSC)." (PMID 36376862, 2022). "ALKBH5 manipulation mediated RMRP suppression, which may be considered as a promising therapeutic target for lung adenocarcinoma." (PMID 34513699, 2021). "Moreover, ALKBH5 downregulates the m6A enrichment on FOXM1 mRNA and promotes cell proliferation and invasion in lung adenocarcinoma." (PMID 33428593, 2021). "Besides, ZC3H13, ALKBH5, YTHDF1, and YTHDF2 were also positively related with each other in lung adenocarcinoma." (PMID 32398949, 2020). "ALKBH5 can upregulate RMRP through the demethylation of m6A, and the tumorigenesis can be proscribed by ALKBH5 knockdown in vitro and in vivo, representing that ALKBH5 may be directly correlated with RMRP function to modulate lung adenocarcinoma tumor cells." (PMID 35534472, 2022).
intrahepatic cholangiocarcinoma (23 papers, 2021 to 2025). A carcinoma that arises from the intrahepatic bile duct epithelium in any site of the intrahepatic biliary tree. "In intrahepatic cholangiocarcinoma (ICC), the loss of ALKBH5 enhanced m6A abundances of PD-L1 transcripts in the 3′-UTR region in a YTHDF2-dependent manner, downregulating its expression." (PMID 36960074, 2023). "For example, ALKBH5 inhibited the expansion and cytotoxicity of T-cell in intrahepatic cholangiocarcinoma." (PMID 40198960, 2025). "For example, depletion of FTO induces suppression of LILRB4 in AML, and ALKBH5 facilitates expression of PD-L1 in intrahepatic cholangiocarcinoma (ICC)." (PMID 36810281, 2023). "Recent studies have reported that ALKBH5 suppressed antitumor T cells by inhibiting PD-L1 mRNA degradation in N6-methyladenosine modification in intrahepatic cholangiocarcinoma." (PMID 36566230, 2022). "A study found that ALKBH5, an important m6A demethylase, regulated PD-L1 expression in intrahepatic cholangiocarcinoma." (PMID 36545327, 2022). "Similarly, knockdown of ALKBH5 in intrahepatic cholangiocarcinoma (ICC) cells increased m6A modifications in the 3′UTR of PD-L1 mRNA, resulting in its degradation via YTHDF2." (PMID 39987091, 2025). "In addition, ALKBH5 suppressed the immune function of antitumour T cells in intrahepatic cholangiocarcinoma (ICC) by upregulating PD‐L1 expression." (PMID 38572667, 2024). "ALKBH5 increased the expression of PD-L1 expression in intrahepatic cholangiocarcinoma (ICC)." (PMID 36835633, 2023). "In intrahepatic cholangiocarcinoma (ICC), the m6A demethylase ALKBH5 has been shown to diminish m6A methylation on PD-L1 mRNA, shielding it from YTHDF2-mediated degradation." (PMID 40034695, 2025). "The demethylase ALKBH5 maintains the stability of PD-L1 mRNA in intrahepatic cholangiocarcinoma (ICC) cells by interacting with PD-L1 mRNA and inhibiting T cell anti-tumor immunity in a PD-L1-dependent manner." (PMID 38762484, 2024). "Furthermore, ALKBH5 was identified to directly regulate the mRNA of PD-L1, a critical immune checkpoint molecule, and thus influence the immune microenvironment and immunotherapy in the intrahepatic cholangiocarcinoma." (PMID 36566230, 2022). "ALKBH5 is an m6A demethylase that coordinates PD-L1 expression in human intrahepatic cholangiocarcinoma (ICC)." (PMID 35279217, 2022). "In addition, ALKBH5 regulated PD-L1 mRNA in intrahepatic cholangiocarcinoma (ICC)." (PMID 34630412, 2021). "In intrahepatic cholangiocarcinoma (ICC), ALKBH5 regulates the tumor immune microenvironment and immunotherapeutic efficacy via modulating the methylation of PD-L1 mRNA." (PMID 36609413, 2023). "ALKBH5 regulated PD-L1 mRNA in a YTHDF2-dependent manner on monocytes/macrophages and infiltration of myeloid-derived suppressor-like cells in the TIME of intrahepatic cholangiocarcinoma (ICC)." (PMID 36225914, 2022). "In addition, in intrahepatic cholangiocarcinoma (ICC), ALKBH5 positively regulates PD-L1 expression in tumor cells and inhibits the expansion and cytotoxicity of T cells through PD-1/PD-L1 signaling." (PMID 35296338, 2022). "Additionally, ALKBH5 regulated TIME by inhibiting the infiltration of MDSC-like cells and promoting PD-L1 expression on monocyte/macrophage cells via YTHDF2 in intrahepatic cholangiocarcinoma (ICC)." (PMID 39718205, 2025). "In intrahepatic cholangiocarcinoma (ICC), ALKBH5 interacts with tumour PD-L1 to remove m6A deposition in the 3’UTR of PD-L1 mRNA, therefore preventing YTHDF2-mediated RNA decay and sustaining PD-L1 expression, which represses the proliferation of cytotoxic T cells." (PMID 36859310, 2023). "Loss of ALKBH5 enhances the m6A modification on the 3’ UTR region of PD-L1 mRNA to promote its degradation in a YTHDF2-dependent manner, thus decreasing the expression of PD-L1 on monocyte/macrophage cells and increasing the infiltration of MDSC-like cells in intrahepatic cholangiocarcinoma (ICC)." (PMID 37015927, 2023).
intrahepatic cholangiocarcinoma (continued). "alkB homologue 5, RNA demethylase (ALKBH5), an m6A demethylase, can orchestrate m6A levels in the 3′UTR of programmed cell death-1 ligand-1 (PD-L1) mRNA, stabilize PD-L1 expression in intrahepatic cholangiocarcinoma (ICC), thus sensitize tumour cells to anti-PD1 immunotherapy." (PMID 34895230, 2021).
cervical cancer (20 papers, 2017 to 2025). A primary or metastatic malignant neoplasm involving the cervix. "PD-L1 expression increased dramatically in cervical cancer tissues and was significantly linked to ALKBH5, FTO, METTL3, RBM15B, YTHDF1, YTHDF3, and ZC3H13 expression levels." (PMID 36091006, 2022). "In cervical cancer, high ALKBH5 expression is linked to aggressive features and poor prognosis." (PMID 39192357, 2024). "The overexpression of ALKBH5 in cervical cancer decreases the expression and stability of circCCDC134, which in turn promotes the growth and metastatic of cancer cells by influencing HIF1A transcription." (PMID 40384875, 2025). "Specifically, we found lower expression of METTL3, METTL14, and WTAP transcripts, while RBM15 and ALKBH5 abundance was elevated in cervical cancer cells." (PMID 38665783, 2024). "LncRNA GAS5-AS1 has been identified as a promoter of ALKBH5-dependent m6A demethylation in cervical cancer, thereby inhibiting the proliferation, migration and invasion of cervical cancer cells." (PMID 35676619, 2022). "For example, the lncRNA GAS5-AS1 enhances the stability of GAS5 by interacting with ALKBH5 to suppress the proliferation of cervical cancer." (PMID 34721523, 2021). "In addition, HDAC6 expression levels were significantly decreased in both HeLa and SiHa cells overexpressing m6A demethylase ALKBH5, suggesting that HDAC6 expression in cervical cancer cells is closely associated with m6A modification." (PMID 39535388, 2025). "Moreover, the zebrafish xenograft experiments showed that HPV-positive cervical cancer cells in which ALKBH5 was silenced were propagated and spread to a lesser extent compared with the negative control group." (PMID 37639643, 2023). "Interestingly, PVT1, one of lncRNA, was influenced by ALKBH5 silencing and associated with MMP2/9 expression in cervical cancer cells." (PMID 37639643, 2023). "On the other hand, the significant decrease in number of migrated and invaded cells that were observed as a consequence of downregulating ALKBH5 expression suggested that the major function of ALKBH5 could be in enhancing metastasis in cervical cancer." (PMID 37639643, 2023). "Since the previous experiments performed in this study have shown that MATAL1 was able to upregulate ALKBH5 expression, it was reasonable to surmise that ALKBH5 could contribute to the development of HPV-positive cervical cancer." (PMID 37639643, 2023). "Studies have found that the ALKBH5-mediated reduction of RNA m6A levels promotes the proliferation of cervical cancer cells, and increasing the m6A levels by inhibiting ALKBH5 may have anticancer effects." (PMID 36814204, 2023). "Furthermore, lncRNA GAS5-AS1 has been shown to suppress the proliferation of cervical cancer cells by interacting with ALKBH5." (PMID 34802433, 2021). "Moreover, lncRNA GAS5-AS1 had been identified as a promoter in ALKBH5-dependent m6A demethylation in cervical cancer, consequently inhibiting proliferation, migration, and invasion of cervical cancer cells." (PMID 34722303, 2021). "However, the results obtained from this study suggest that PVT1 could be involved in MMP2 and MMP9 regulation by ALKBH5 in cervical cancer cells." (PMID 37639643, 2023). "ALKBH5-mediated demethylation destabilizes circCCDC134 via YTHDF2, significantly impacting cervical cancer metastasis." (PMID 39192357, 2024). "Collectively, these results demonstrated that ALKBH5, as a downstream target of MATAL1, was also able to promote HPV-positive cervical cancer development." (PMID 37639643, 2023). "For example, lncRNA GAS5-AS was reported to repress tumorigenesis and metastasis of cervical cancer by enhancing GAS5 stability and regulating m6A modifications of GAS5, which was dependent on ALKBH5 and YTHDF2." (PMID 35524319, 2022). "LncRNA GAS5-AS1 establishes interaction with demethylase ALKBH5 to increase the stability of GAS5, thereby suppressing the growth and metastasis of cervical cancer." (PMID 34950253, 2021).
cervical cancer (continued). "On the other hand, knocking-down adenosine demethylases (FTO and ALKBH5) or overexpressing adenosine methyltransferases (METTL3 and METTL14) suppressed cervical cancer development in vivo." (PMID 29228737, 2017). "In addition, the present study will demonstrate that ALKBH5 exerts roles in the proliferation and metastasis of HPV-positive cervical cancer cells." (PMID 37639643, 2023). "Given the powerful roles of ALKBH5 in m6A modification, it is worthwhile to identify the potential targets of ALKBH5 at the whole transcriptome level in HPV-positive cervical cancer using MeRIP-seq assay, which would be further investigated in our future study." (PMID 37639643, 2023). "Similarly, the lncRNA GAS5-AS (antisense to GAS5) enhances GAS5 stability by binding to ALKBH5 and controlling m6A modifications of GAS5 in cervical cancer." (PMID 35063010, 2022). "Interestingly, LncRNA GAS5-AS1, the antisense RNA of GAS5, has been detected to interact with GAS5 and enhanced its stability through decreasing ALKBH5-mediated GAS5 m6A modification, therefore reducing the proliferation, migration and invasion of cervical cancer cells." (PMID 37365581, 2023). "Due to limited funding, the interactions between MALAT1 and ALKBH5, as well as the m6A methylation level in HPV-positive cervical cancer or clinical patient samples, were not evaluated in this study." (PMID 37639643, 2023).
non-small cell lung carcinoma (20 papers, 2020 to 2025). A group of at least three distinct histological types of lung cancer, including non-small cell squamous cell carcinoma, adenocarcinoma, and large cell carcinoma. "For instance, ALKBH5 is aberrantly expressed in non-small-cell lung cancer (NSCLC) and its abnormal expression is obviously associated with unfavorable patient’s prognosis." (PMID 38545555, 2024). "ALKBH5 promotes non-small cell lung cancer progression by regulating cancer and tumor-associated macrophage behavior through the JAK2/p-STAT3 pathway and the expression of CCL2 and CXCL10, respectively." (PMID 38872221, 2024). "Extracellular vesicles (EVs) released from cigarette smoke extract (CSE)-induced M2 macrophages affect ALKBH5 activity in non-small cell lung cancer (NSCLC)." (PMID 39192357, 2024). "The N6-methyladenosine (m6A) demethylase, ALKBH5 (alkB homolog 5), is overexpressed in non-small cell lung cancer." (PMID 38872221, 2024). "In vitro and in vivo assays were performed to determine the contribution of ALKBH5 to the development of non-small cell lung cancer." (PMID 38872221, 2024). "Consistently, UBE2C has been found to be epi-transcriptionally stabilized with the maintenance of lower m6A levels within its mature RNAs in response to the increase in ALKBH5 expression in non-small cell lung cancer." (PMID 36551544, 2022). "A previous study had reported that ALKBH5 suppresses tumor progression in non-small cell lung cancer in a YTHDF1-dependent manner." (PMID 34079761, 2021). "However, by focusing on genes linked to lipid peroxidation, both ALKBH5 and FTO can also induce ferroptosis in non-small cell lung cancer (NSCLC) and oral squamous cell carcinoma." (PMID 40271153, 2025). "Bioinformatic analysis, colorimetric assay to determine m6A RNA methylation, dual luciferase reporter assay, RNA/m6A-modified RNA immunoprecipitation, RNA stability assay, and RNA sequencing were used to investigate the regulatory mechanism of ALKBH5 in non-small cell lung cancer." (PMID 38872221, 2024). "ALKBH5 was upregulated in primary non-small cell lung cancer tissues." (PMID 38872221, 2024). "Forced ALKBH5 expression can stabilize ubiquitin-conjugating enzyme E2C (UBE2C) epi-transcriptionally via the maintenance of lower m6A levels within its mature RNAs in non-small cell lung cancer." (PMID 36551544, 2022). "ALKBH5 also acts as a tumor suppressor in non-small cell lung cancer (NSCLC)." (PMID 33790968, 2021). "Similarly, Yu found that in KRAS-mutant non-small cell lung cancer cells, cisplatin treatment increased overall m6A modification levels by regulating the post-translational modifications (PTMs) of ALKBH5, thereby enhancing DNA damage repair capacity and promoting resistance to platinum-based drugs." (PMID 40719884, 2025). "Besides, it was reported recently that ALKBH5 could inhibit miR-107/LATS2-mediated YAP activity by inhibiting tumor growth in non-small cell lung cancer." (PMID 35279083, 2022). "In non-small-cell lung cancer (NSCLC), ALKBH5 mediated m6A modification of JAK2 mRNA, activated the JAK2/p-STAT3/CCL2/CXCL10 axis, leading to the recruitment of PD-L1 + TAMs and promoting M2 macrophage polarization." (PMID 39987091, 2025). "JAK2 was identified as a target of ALKBH5-mediated m6A modification, which activates the JAK2/p-STAT3 pathway to promote non-small cell lung cancer progression." (PMID 38872221, 2024). "ALKBH5 inhibits tumor growth and metastasis by inhibiting miR-107/LATS2 mediated YAP activity in non-small cell lung cancer." (PMID 36614216, 2023). "HuR-miR-107: In non-small cell lung cancer cells (NSCLC, A549, H1299, Calu6 and H520) ALKBH5 (AlkB homolog 5), inhibits Hippo/YAP signaling and reduces cancer cell proliferation, migration, and invasion." (PMID 35884580, 2022). "For example, ALKBH5 inhibits tumour growth and metastasis by abolishing the expression and activity of YAP in non-small cell lung cancer." (PMID 36028854, 2022).
non-small cell lung carcinoma (continued). "The demethylase ALKBH5 can remove the m6A modification of YAP, which results in its reduced expression in the non-small-cell lung carcinoma (NSCLC) through an YTHDF1/2-dependent pathway." (PMID 33926508, 2021). "In addition, ALKBH5 inhibits tumor growth and metastasis via abolishing expression and activity of YAP in non-small cell lung cancer." (PMID 32772918, 2020).